EGFR (epidermal growth factor receptor)
Diseases named in the same sentence as EGFR in open-access papers (continued):
Sharing a sentence is not in itself a finding about the gene and the disease.
tumor (continued). "Furthermore, we confirmed that the blockade of EGFR using si-EGFR and treatment with neutralizing antibodies against EGFR prevented HB-EGF-mediated tumor growth." (PMID 39419989, 2024). "Docking studies were carried out on the epidermal growth factor receptor (EGFR) enzyme, involved in tumor initiation, angiogenesis, and metastasis, demonstrating that the internal oxime moiety of the scaffolds 10b and 10e forms extra hydrogen bonds with specific amino acids in the receptor’s cleft." (PMID 39598729, 2024). "Therefore, the aim of this work was the immunohistochemical characterization of EGFR, VEGFR-2, COX-2, Ki-67, survivin and E-cadherin in canine nasal sarcomas compared to carcinomas and to compare the expression to tumor size (T-categories)." (PMID 39268521, 2024). "The single gene analysis showed EGFR exon 19 deletion in the resected tumour but negative for BRAF V600E." (PMID 39139611, 2024). "A further improvement in this respect could be achieved by using anti-EGFR antibodies optimized to deliver enhanced ADCC activity, which demonstrated a superior anti-tumor activity as compared to cetuximab in mouse models." (PMID 38510242, 2024). "When EGFR and HER2 are overexpressed in tumour cells, these cells multiply rapidly." (PMID 38773634, 2024). "The dynamic changes observed in key mutations such as BRAF, APC, GNAS, EGFR, and PIK3CA suggest that ctDNA analysis can offer unique insights into tumor evolution that are not captured by traditional tissue biopsies." (PMID 39796090, 2024). "These modifications are aimed at enhancing their interaction with specific tumor targets such as EGFR or increasing their selective toxicity towards tumor cells as opposed to healthy ones." (PMID 39858410, 2024). "If ROS levels in tumor cells are low, the probe will not fluoresce, indicating that the tumor cells are not sensitive to EGFR-TKI and that the patient is not suitable for EGFR-TKI treatment." (PMID 39451714, 2024). "The central hypothesis posits that concurrent inhibition of EGFR and HER2 using osimertinib and T-DM1 could reinstate tumor responsiveness." (PMID 39015563, 2024). "Therefore, it is critical to understand that in order to get the most robust efficacy from EGFR targeted CAR T cells, the tumor microenvironment must also be targeted and manipulated." (PMID 39364321, 2024). "MAPK signaling rebound is recognized as an essential resistance mechanism in BRAF-mutant tumor treatment, so we tested whether a MOGAT3 inhibitor combined with dual therapy would inhibit p-ERK rebound more profoundly than anti-BRAF/EGFR treatment." (PMID 39436710, 2024). "We compared EGFR‐positive and ALK‐positive tumors in a relatively homogeneous group, which may have clarified the tumor marker difference." (PMID 38400801, 2024). "Lysis of EGFR-negative CT26 tumor cells was negligible in the presence of serum containing either LiTE- or Albu-LiTCo." (PMID 39835115, 2024). "Furthermore, EGFR/STAT3 and Notch signaling support self-renewal and proliferation of GBM stem cells to drive tumor progression." (PMID 39513361, 2024). "DM001 was conjugated to MMAE via a protease-cleavable linker to generate the DM001 bsADC, which showed more potent cell-killing capacity in EGFR/TROP2-positive cells than single-target positive cells and showed potent anti-tumor activity in lung and pancreatic cell line xenografts and PDXs." (PMID 39065587, 2024). "The tumor exhibited no IDH1, IDH2, TERT, H3, or BRAF mutation, and had no EGFR amplification, no MYB rearrangement, and a positive MGMT status." (PMID 39227460, 2024). "Immunologic examination of patient tumors showed that the drug reached its target and was found to efficiently dephosphorylate EGFR; however, gefitinib alone was not enough to stop tumor growth signaling." (PMID 38396993, 2024).
tumor (continued). "The survival rate for patients with tumor-expressing membranous EGFR was nonsignificantly higher than those who were expressing cytoplasmic EGFR in EGFRWT and EGFRM cases (p = 0.086 and 0.181, respectively)." (PMID 38338651, 2024). "The EGFR-Vδ2hi-lo bsVHH-albumin retained the ability to support Vγ9Vδ2 T-cell enrichment and expansion in healthy donor PBMC and also triggered Vγ9Vδ2 T-cell degranulation and lysis of SW480 tumor cells." (PMID 39493452, 2024). "When combining the three models, the independent predictive factors for EGFR mutations were non-fibrotic ILA, female sex, and small tumor size, with an AUC value of 0.920 (95% confidence interval[CI]: 0.861–0.978, p < 0.001)." (PMID 38783331, 2024). "Also, we tested the expression of EGFR, ErbB2, p-AKT, and p-mTOR in 4 groups of tumor tissues through western blot." (PMID 39075515, 2024). "CMTM family proteins also exert their biological functions by signaling pathways that correlate with cell growth and migration, including the EGFR, WNT and JAK2/STAT3 signaling pathways, indicating that CMTM proteins are potential targets for altering tumor progression and metastasis." (PMID 38223763, 2024). "This specific type of tumour, characterised by high CD151 and the absence of EGFR mutations, was associated with poorer survival outcomes in patients from both our study cohorts." (PMID 38982031, 2024). "Meanwhile, the ADC did not exert any significant tumor restriction on EGFR-low CAL51 xenografts compared with the same controls." (PMID 38772416, 2024). "Differential gene expression showed that, in clinical patients, the level of EGFR was observed to be greater in healthy tissue as compared to tumor tissue, and patients with a negative ER status were more likely to have a high EGFR expression." (PMID 39202273, 2024). "In addition, YAP-TEAD inhibitors, XAV939 and MYF-01-37, enhanced EGFR/MEK inhibitor-induced apoptosis, playing a synergistic role in tumor." (PMID 38499647, 2024). "Dual targeting antibodies combining specificities for HER2 and B7-H3, or HER2 and EGFR may be more specific than bispecific antibodies targeting HER2 alone and thereby reduce on-target off-tumor side effects." (PMID 39139449, 2024). "In this study, we used in vitro longitudinal live cell imaging, clonogenic assays, flow cytometry, immunofluorescence, in vivo hypoxia imaging and longitudinal tumor monitoring to elucidate the impact of dual HER2 and EGFR inhibition on cellular and molecular mechanisms of radiosensitivity." (PMID 38355949, 2024). "In our case, immunohistochemistry revealed epidermal growth factor receptor expression on tumor cells, but we did not have enough evidence in favor of cetuximab to use it in the elderly patient." (PMID 39040982, 2024). "The violin plot showed the cell-cell interactions while giving the different ligands and receptors in the EGF signaling pathway, and the results showed that C1 SRSF7+ MCs subtype and tumor-cells were mainly contacted with AREG as a ligand and EGFR or ERBB2 as receptors." (PMID 39430754, 2024). "Among these patients, the incidence of neurological events was 30%, with no cases of CRS or off-tumor toxicity targeting EGFR." (PMID 39506843, 2024). "Although TNBC does not overexpress HER2 receptors, it has been observed that EGFR protein expression is present in this specific type of tumor, making it an attractive target for immune and radiopharmaceutical treatments." (PMID 39769315, 2024). "For instance, the epidermal growth factor receptor that promotes angiogenesis and activation of EGFR signalling is known to enable an intravasation-sustaining microenvironment in the developing primary tumour." (PMID 39770497, 2024). "The results showed that RT increased the percentage of CD8+ positive CAR-T cells (CD3 + CD8 + EGFR + ) and effector CAR-T cells (CD3 + EGFR + CD45RA + CCR7-) in peripheral blood 7 days after CAR-T injection, highlighting the enhanced anti-tumor activity of the synergy therapy." (PMID 39578426, 2024).
tumor (continued). "However, we used I5270, an antibody that neutralizes human IL11, to verify the inhibition of EGFR phosphorylation and PDL1 expression in tumor cells in vitro." (PMID 38696655, 2024). "In terms of clinical implications, in one patient with previously known NSCLC and EGFR mutation, plasma and GSF-s allowed for the detection of an EGFR exon 20 p.T790M resistance mutation, despite the absence of tumor cells on pathologic examination." (PMID 38328474, 2024). "In cultured NSCLC cells or xenograft tumor, the expression of HDGF is positively correlated with the activation of these pathways and the resistance to EGFR TKI; knocking down HDGF diminishes the activation of these pathways and sensitizes the cells to TKI inhibition." (PMID 39041204, 2024). "In addition, FKC can affect NPC tumor growth and metastasis in vivo by regulating the HSP90B1/EGFR pathway." (PMID 38711062, 2024). "Additionally, CD109’s interaction with EGFR could amplify pro-inflammatory cytokine production, such as IL-6 and IL-8, by activating downstream pathways like Akt/mTOR and NF-κB, thereby enhancing tumor growth, immune suppression, and potentially contributing to chemoresistance." (PMID 39990858, 2024). "Many pan-cancer tumor targets, including human epidermal growth factor receptor 2 (HER2), mucin 1 (MUC1), and EGFR, are also expressed at high levels in UCs and may serve as therapeutic targets." (PMID 38789450, 2024). "The tumors were defined by nine tumor states, each characterized by the differential activity of nine key pathways: NRF2-PPP, NFkB-SRC-JUN, TCA Cycle, DNA Repair-MYC-E2F, PI3K-EMT-Stem, WNT-BCAT-AKT, NFkB-IRF-KLF5, EGFR-p63, and EMT-ZEB1." (PMID 38505587, 2024). "When NIR-PIT using the EGFR Affibody–IR700Dye conjugate is considered for EGFR-positive SGC, near-infrared light can be irradiated directly using an optical fiber diffuser inserted into the tumor." (PMID 38542206, 2024). "A previous study reported a non-inflamed tumor microenvironment (TME) with high CD4+ Treg cell infiltration in pre-treated EGFR-mutant NSCLC." (PMID 38897205, 2024). "Taken together, IHC analysis demonstrated that EGFR and MUC1 were present at medium to high levels in the majority of LUAD and CRC samples, and in line with single-cell analysis, they tended to be co-expressed on tumor cells." (PMID 39664199, 2024). "For instance, combining EGFR inhibitors with inhibitors of key signaling molecules like MEK and C-RAF could not only more comprehensively suppress tumor proliferation signals but also decrease the adaptive resistance mechanisms of tumor cells to single agents." (PMID 39592929, 2024). "Though there is no level 1 evidence due to the rarity of the tumour with dual EGFR and ROS1 positivity, literature supports the use of TKI rather than chemotherapy in such cases." (PMID 38425761, 2024). "The efficacy of BI-4020 was also evaluated in vivo, and a significant anti-tumor effect against the EGFR-del19/T790M/C797S/L718M quadruple mutant was confirmed using BI-4020 with an anti-EGFR antibody combination without any apparent side effects." (PMID 38396251, 2024). "TargomiRs is a tumor suppressor that encapsulates a miR-16 mimic within non-viable bacterial microcells, specifically targeting the epidermal growth factor receptor (EGFR) (NCT02369198)." (PMID 39479511, 2024). "Therefore, it is necessary for the kinase domains of EGFR and HER2 to be accessible to lapatinib and this is most likely to occur when they are situated in the cytoplasm or plasma membrane of tumor cells." (PMID 39257973, 2024). "A potential advantage of our strategy is that the ability of EGFR BATs to recruit and activate endogenous immune cells in the TME may enhance systemic-specific cellular and humoral tumor immunity." (PMID 38263486, 2024). "DB-1310 demonstrated tumor-suppressive activity against HER3-expressing tumors, indicating that it could be new therapeutic selection for the EGFR-TKI refractory NSCLC patient." (PMID 38632563, 2024).
tumor (continued). "EGFR and HER2 were useful targets for driving T cell infiltration and tumor ablation." (PMID 38650005, 2024). "Overexpression of EGFR has also been noted in over 50% of TNBC cases, indicating that EGFR could be the driver of tumor progression." (PMID 38532948, 2024). "Consistent with LAMC2 promoting EGFR translation, EGFR IHC staining in Cohort 4 showed a significantly higher staining score in iCCA tumors compared to bile ducts (p < 0.001) and a positive correlation with LAMC2 staining in iCCA tumor tissues (p = 0.05)." (PMID 38526177, 2024). "Tumor reactivity cell scores are higher in CD8+ T cells from tumors of smokers than from tumors of non-smokers (P = 0.002) and are higher in wild-type EGFR tumors than in mutated tumors (P = 0.180)." (PMID 37735262, 2024). "Interestingly, based on previous studies, IGFBP3 targets the regulation of classical signaling pathways and key molecules such as MAPK, EGFR, AKT, and EMT to regulate tumor proliferation and metastasis." (PMID 38463397, 2024). "Indeed, we examined the importance of analyzing the anti-EGFR antibody–drug conjugates (ADC) developed to overcome resistance and/or stimulate the tumor host’s immunity against CRC growth." (PMID 39000238, 2024). "Additionally, potential anti-tumor cellular mechanisms were explored through molecular docking, which was used to predict the binding mode of 4c with METAP2 and EGFR, suggesting that the C=O part of the pyridone moiety likely played a crucial role in binding." (PMID 39273581, 2024). "This study explores the impact of the epithelial cytokine heparin-binding epidermal growth factor (HB-EGF) and its receptor epidermal growth factor receptor (EGFR) on the pathogenesis of CAC and CRC, particularly in the regulation of microRNA-driven tumor growth and protease expression." (PMID 39419989, 2024). "Within the context of a multicenter, phase 1b and 2 study, this investigation focused on individuals characterized by a high tumor mutational burden (TMB) and the absence of EGFR or ALK alterations." (PMID 39015563, 2024). "Quantitative analysis after gargling with Nimotuzumab-ICG (0.4 mg/ml) showed that EGFR expression was specifically highly expressed in tumor tissues but not in normal mucosa tissues (top, 23.9 ± 1.17 vs 3.01 ± 0.24, **** P < 0.0001)." (PMID 39183296, 2024). "The EGFRxHER2 T-BsAb, bearing only one Fab for EGFR and HER2, could be considered ‘tumor monovalent’ in the context of these single-positive PDAC lines." (PMID 38650005, 2024). "Animals treated with laser irradiation and anti-EGFR-MPB (group IV) showed notable inhibition of tumor growth, with no malignant tissues detected after treatment." (PMID 39525484, 2024). "The pre-existing anti-EGFR-specific antibodies elicited by DTT-EG vaccination can effectively control tumor growth and, in conjunction with the immune system, impede and expedite tumor regression." (PMID 39766327, 2024). "Pharmacological resistance occurs when cancer cells theoretically retain intrinsic drug sensitivity, but the concentration of EGFR-TKIs at the target tumor sites is not sufficient to obtain an adequate pharmacological response." (PMID 38732063, 2024). "Overall, we show that EGF may activate an EGFR-mediated signaling pathway through p38β MAPK, to upregulate the invasion factor ODZ1, which may initiate morphological changes for tumor cells to invade the surrounding parenchyma." (PMID 38727302, 2024).
tumor (continued). "The high specificity of the heterodimeric EGFRxHER2 T-BsAb for EGFR+HER2+ double-positive PDAC tumors could offer a strategy to spare healthy single-positive tissues and reduce on-target/off-tumor side effects." (PMID 38650005, 2024). "One study shows the effectiveness of cetuximab in PC based on the expression of epidermal growth factor receptor in the tumor but, unfortunately, the patient did not survive." (PMID 39040982, 2024). "Nivolumab plus ipilimumab is indicated in the USA and other countries for the first-line treatment of adults with metastatic NSCLC with PD-L1 ≥ 1% and no EGFR or ALK genomic tumor aberrations." (PMID 38893141, 2024). "We also demonstrate the efficacy of targeting BCL-XL in combination with EGFR-TKI treatment to prevent resistance, not only in cell lines but in transgenic mice, which better reflect characteristics of tumors and the tumor microenvironment, as well as anti-tumor immune responses." (PMID 39122703, 2024). "HEYL, SLC2A3, and FBN1 were found to mediate tumor progression and chemoresistance mainly by facilitating angiogenesis and EMT, while CERCAM, ANXA1, and SPOCD1 promoted tumor progression through the PI3K/AKT and EGFR signaling pathways." (PMID 39033778, 2024). "EGFR and PD-L1 expression levels were distinctly higher in OSCC tumors than in para tumor tissues." (PMID 39183296, 2024). "Heterodimers of MET with EGFR, HER2, HER3, or RET exhibit distinct roles in tumor development." (PMID 39201787, 2024). "Furthermore, afatinib, a second‐generation EGFR‐TKI, potently inhibits p.L747P mutant cells, reduces EGFR phosphorylation and downstream signaling, and significantly suppresses p.L747P mutant tumor growth." (PMID 38572952, 2024). "Epidermal growth factor receptor (EGFR) is located on the cell membrane surface and is a receptor for cell proliferation and signal transduction, and its expression status is related to tumor progression and prognosis." (PMID 39624043, 2024). "Binding to the EGFR triggers intracellular signaling events through at least three major pathways (the AKT, MAPK, and STAT pathways), leading to proliferation, invasion, angiogenesis, metastasis, and inhibition of apoptosis (uncontrolled tumor growth)." (PMID 39429333, 2024). "Although TNBC does not overexpress HER2 receptors, it has been observed that EGFR protein expression is present in this specific type of tumor." (PMID 39769315, 2024). "This approach enables CAR-T cells to effectively distinguish between tumor cells and unactivated EGFR present in normal tissues, thereby reducing toxicity to normal tissues and enhancing therapeutic specificity for EGFR-positive solid tumors." (PMID 39506843, 2024). "Moreover, various factors related to the TME (e.g., tumor‐infiltrating lymphocytes [TIL]) experienced significant changes before and after the development of resistance to EGFR‐TKIs." (PMID 39631794, 2024). "Imaging and biodistribution studies at 48 h p.i. revealed high uptake and retention in the tumour, which was twofold greater for EGFR-targeted AuNPs (197% ID/g) than non-targeted AuNPs (99% ID/g)." (PMID 38703297, 2024). "Furthermore, a recent study in the field of photoimmunotherapy described the development of an approach in which NIR-PIT targeted EGFR and human EGFR2 expressed in tumor tissues as well as cytotoxic T cells and regulatory T cells." (PMID 38515576, 2024). "In this regard, the combination of EGFR-TKIs with anti-angiogenic drugs that induce the normalization of tumor vasculature has improved the clinical outcome of EGFR-mutant NSCLC patients, possibly also through an enhanced delivery of anti-EGFR agents to the target tumor sites." (PMID 38732063, 2024).